SMAD2 (SMAD family member 2)
Diseases named in the same sentence as SMAD2 in open-access papers (continued):
Sharing a sentence is not in itself a finding about the gene and the disease.
breast carcinoma (continued). "Conversely, expression of Smad2, Smad3, alone or together promoted an EMT-like phenotype even in the absence of exogenous TGFβ in breast carcinoma organoids." (PMID 37414747, 2023). "For example, lung and breast cancers lacking RASSF1A display hyperactive TGFβ signaling and tumor invasion via the YAP-dependent nuclear localization of Smad2." (PMID 31212916, 2019). "Specifically, OXSR1 has been previously reported to mediate the TGF-β signaling pathway in breast cancer, promoting epithelial-mesenchymal transition (EMT) and metastasis through the phosphorylation of Smad2/3, EXOSC10 is a novel candidate factor that had not been identified before." (PMID 39619656, 2024). "Although the role of other hub genes in breast cancer has not been specifically reported, studies have shown that they play an essential role in other cancers, such as BUB1 promotes proliferation by activating SMAD2 phosphorylation." (PMID 35456460, 2022). "During breast cancer bone metastasis progression, the TGF-β induced bone metastatic genes expression were found depend on SMAD3 but not SMAD2, and knockdown of SMAD3 in MDA-MB-231 cells inhibited bone metastasis, while SMAD3 knockdown led to a more aggressive phenotype." (PMID 32746934, 2020). "Smad2 and Smad3 are highly homologous, but may play non-redundant or even opposing roles in TGF-β signaling, so we first wished to determine which Smad was more important for tumor suppression in the MCF10-based breast cancer model." (PMID 24890385, 2014).
liver fibrosis (204 papers, 2007 to 2026). "PRDX3 silencing exacerbates liver fibrosis and HSC activation, while HSC overexpression of PRDX3 alleviates liver fibrosis caused by CCl4 by inhibiting HSC activation through the mitochondrial ROS/TGF-β1/Smad2/3 signalling pathway." (PMID 40462224, 2025). "The roles of JAK2/STAT3 and TGF-β/Smad2/3 regulatory pathways are examined specifically as it is found to be a crucial pathogenic mediator of liver fibrosis." (PMID 41293246, 2025). "SMAD2/3 are two important downstream genes of the TGF-β signaling pathway that are associated with liver fibrosis and carcinogenesis." (PMID 38385079, 2024). "As liver fibrosis is closely connected to liver cancer, the pathogenic roles of SMAD2 and SMAD3 were further explored in liver cancer in TCGA." (PMID 37790613, 2023). "TGF-beta and lipopolysaccharide (LPS), two important factors in liver fibrosis and inflammation, cause HSCs to express miR-942 via Smad2/3 and NF-p50 binding to the miR-942 promoter, respectively." (PMID 37621844, 2023). "In the present study, we determined the underlying mechanism by which Daxx functions in liver fibrosis and we identified its antifibrotic role as a key factor that modules Smad2-mediated TGF-β signaling." (PMID 34359912, 2021). "A similar study found that the high expression of Smad-2 and Smad-4 was associated with liver fibrosis in rats using in situ hybridization." (PMID 28086769, 2017). "CCl4-induced hepatic fibrosis caused increased phosphorylation of Smad2 and Smad3 when compared to that of the controls." (PMID 25373883, 2015). "Moreover, Hic-5 functions as a scaffold for the TGF-β/Smad2 pathway and its deficiency significantly attenuated mouse liver fibrosis because of reduced collagen production." (PMID 31673109, 2019). "Previous researches revealed that Nogo-b could cause hepatic fibrosis through TGFβ1/Smad2 signaling pathway." (PMID 29050340, 2017). "In the present study, CCl4-induced liver fibrosis was associated with a marked activation of Smad2/3 but a loss of Smad7, suggesting that the imbalance between Smad2/3 and Smad7 signaling could be important in the pathogenesis of liver fibrosis." (PMID 22363627, 2012). "The recent identification of PZH’s modulation of the EGFR/JAK1/STAT3 pathway enhances its known inhibitory effects on the TGF-β1/Smad2 axis, thereby elucidating a multifaceted mechanism against hepatic fibrosis." (PMID 41181146, 2025). "Collectively, miR-125a-5p can inhibit HSCs activation and alleviate liver fibrosis to some extent through the TGF-β/Smad2/3 signaling pathway and autophagy." (PMID 40890107, 2025). "Further mechanistic investigations revealed that miR-125a-5p attenuated HSC activation while ameliorating liver fibrosis through regulating the TGF-β/Smad2/3 pathway and autophagy." (PMID 40890107, 2025). "Past studies have shown that SMAD3 is the key progenitor in the induction of liver fibrosis, although both SMAD2 and SMAD3 are substrates that are significantly activated in liver fibrosis." (PMID 39937012, 2025). "RTN4 can regulate liver fibrosis via facilitating the TGFβ/Smad2 signaling pathway in myofibroblasts." (PMID 39972424, 2025). "PZW mitigated hepatic fibrosis, with its effect associated with the inhibition of the IL-6/JAK2/STAT3 and TGF-β/Smad2/3 signaling pathways and through raising the MMP1/TIMP-1 ratio." (PMID 41293246, 2025). "In the CCl4-induced liver fibrosis model, phosphorylation and nuclear translocation of Smad2/3 were significantly increased." (PMID 40483470, 2025). "Lysine acetylation can regulate Smad2 transcriptional activity, which inhibits hepatic stellate cells activation and liver fibrosis." (PMID 40435176, 2025). "Through gain- and loss-of-function experiments, we show that Gdf10 overexpression attenuates liver fibrosis by competitively binding TβR2, blunting SMAD2/3 phosphorylation, and suppressing TGFβ1-driven ECM deposition." (PMID 41281741, 2025).
liver fibrosis (continued). "As for liver fibrosis, results indicated that Mig alleviated CCl4-induced liver fibrosis by inhibiting the phosphorylation of Smad2/3 induced by hepatic stellate cells." (PMID 39934657, 2025). "Death‐associated protein 6 (Daxx) interfered with Smad2 acetylation to reduce the transcriptional activity of Smad2, alleviating liver fibrosis in a thioacetamide‐induced fibrosis mouse model." (PMID 39866837, 2025). "PZW mitigated hepatic fibrosis in association with IL-6/JAK2/STAT3 and TGF-β/Smad2/3 signaling pathway inhibition favoring MMP1/TIMP-1 ratio that attenuated collagen deposition and promoted collagen degradation." (PMID 41293246, 2025). "Based on correlation between Sirt6 and fibrosis/Smad signaling pathway, it had been reported that Sirt6 directly interacted with Smad2 in hepatic fibrosis and there was a physical interaction between Sirt6 and Smad3 in hepatic stellate cells." (PMID 38789630, 2024). "The activation of the TGF-β/SMAD signaling pathway in HSCs resulted in the upregulation of several key genes associated with hepatic fibrosis, including TIMP1, SMAD2, SMAD3, COL1A1, and MMP2, as well as increased secretion of MMP-9 protein." (PMID 39201682, 2024). "The anti-fibrotic function of Sirt6 was achieved by regulating the TGFβ-Smad2/3 pathway in stellate cells activation as well as liver fibrosis." (PMID 38789630, 2024). "A mechanistic study elucidated that the regulatory effect of LRRC1 on liver fibrosis is due to its ability to promote the stability of p-Smad2/3." (PMID 38473980, 2024). "Specifically, GDF15 has been found to promote the activation of hepatic stellate cells, a key event in the development of liver fibrosis, by enhancing the expression of fibrotic markers and the phosphorylation of SMAD2 and SMAD3 proteins." (PMID 39697329, 2024). "Numerous studies have shown that abnormal activation of SMAD2/3 usually promotes the progression of liver fibrosis." (PMID 38385079, 2024). "The results of the hepatic fibrosis study reinforce our findings in renal fibrosis, where TA’s inhibition of the TGF-β/Smad2/3 cascade parallels its effects on other fibrotic pathways observed in liver fibrosis." (PMID 39857346, 2024). "miR-488-5p overexpression restrained HSCs activation and hepatic fibrosis via restraining TET3/TGF-β/SMAD2/3 signaling pathway." (PMID 36001230, 2023). "In our study, we discovered that AKF-PD decreased the protein expression of TGF-β1, p-Smad2 and p-Smad3 in the CCl4-induced rat liver fibrosis model." (PMID 37790613, 2023). "The in-vitro research indicates that andrographolides administration can prevent liver fibrosis by blocking the TGF-1/Smad2 as well as TLR4/NF-kβ p50 pathways and attenuating the expression of profibrotic and proinflammatory proteins." (PMID 36985782, 2023). "The phosphorylation of Smad2/3 is responsible for the development of liver fibrosis, and its phosphorylation is activated by TGF-β1." (PMID 37324954, 2023). "The phosphorylation of Smad2/3 plays an important role in blocking the downstream signaling pathway during the development of liver fibrosis." (PMID 37324954, 2023). "TLR2 triggered TGF-β1/Smad2/3 and p38/AKT signaling pathways played crucial roles in activating myofibroblasts and promoting the production of IL-6, which exacerbated liver fibrosis caused by C. sinensis." (PMID 36693049, 2023). "Smad7 acts as an inhibitor, which is also a target of miR21, prevents liver fibrosis by inhibiting Smad2/3." (PMID 38202710, 2023). "In summary, we demonstrated that oxoglaucine significantly suppresses TGFβ-induced hepatic fibrosis, and that regulation of Smad7 levels is an important factor in the inhibition of Smad2 phosphorylation." (PMID 37446633, 2023). "It has been pointed out that with the aggravation of liver fibrosis, the expression of SMAD2 and SMAD3 increases." (PMID 37446187, 2023). "Our study provided some implications about how liver fibrosis was connected with liver cancer by SMAD2/SMAD3 and autophagy." (PMID 37790613, 2023).
liver fibrosis (continued). "In this study, SOEE effectively inhibited the phosphorylation of SMAD2/3 in HSCs to reduce liver fibrosis." (PMID 37686810, 2023). "In a mouse model, SIRT6 alleviated liver fibrosis by the deacetylation of Smad2, inhibited the TGF-β-induced phosphorylation and nuclear localization of Smad2, and decreased the transcription of TGF-β/Smad2 signaling." (PMID 38203666, 2023). "CGA upregulates Smad7 expression, downregulates p-Smad2, p-Smad3, and p-Smad2/3 levels in vitro and in vivo, and has been shown to inhibit CCl4-induced liver fibrosis in Sprague-Dawley rats." (PMID 38202710, 2023). "We highlight that miR-488-5p restrains the activation of HSCs and hepatic fibrosis via targeting TET3 which is involved in the TGF-β/Smad2/3 signaling pathway." (PMID 36001230, 2023). "The results showed that the expression of p-Smad2/3 was significantly up-regulated after CCl4-induced liver fibrosis and was attenuated by indirubin treatment in a dose-dependent manner." (PMID 37605732, 2023). "Recent studies demonstrated that in a rat model of carbon tetrachloride-induced liver fibrosis, the expression of p-Smad2 and p-Smad3 in the liver was significantly increased." (PMID 36474240, 2022). "Smad4 is a core mediator of the TGF-β signaling pathway that can interact with Smad2/3 to transmit upstream Smad signals and promote the occurrence and development of liver fibrosis." (PMID 36232998, 2022). "ARK5, in turn, can promote TGF-β-Smad2/3 signaling, which forms a positive feedback loop, ultimately leading to liver fibrosis." (PMID 36361872, 2022). "A recent study has shown increased hepatic canonical activation of Smad2/3 in an experimental model of liver fibrosis induced by CCl4 and thioacetamide." (PMID 36232707, 2022). "In mice, a lncRNA known as LFAR1 has been shown to bind with SMAD2/3, two proteins involved in liver fibrosis, indicating a potential role that lncRNAs have in signaling pathways that promote liver fibrosis, such as the TGFβ/Notch signaling pathway." (PMID 36005827, 2022). "According to the present study findings, RF can reduce liver fibrosis by altering TGF-β/Smad signaling by decreasing protein expression of Smad2/3 phosphorylation and Smad4 formation, which results in down-regulation of Col1A1 and α-SMA transcriptions." (PMID 35549741, 2022). "Inhibition of SMAD3 decreased collagen I expression while Smad2 increased collagen I expression, and Smad4 is crucial in liver fibrosis by supporting SMAD3 activity." (PMID 36482069, 2022). "In vivo, TGF-β1/Smad2 signaling was up-regulated in the CCl4-induced hepatic fibrosis model, whereas PZH treatment curbed CCl4-induced high expression of TGF-β1 and p-Smad2." (PMID 36188553, 2022). "BDL-induced liver fibrosis was aggravated with increased phosphorylation of SMAD2/3 and decreased levels of SMAD7 by global or liver-specific Prom1 deficiency but not by cholangiocyte-specific Prom1 deficiency." (PMID 36038590, 2022). "TGF-β1 modulate liver fibrosis by activating Smad2 and Smad3 pathway, whereas Smad7 is known as an inhibitor of TGF-β112." (PMID 36482069, 2022). "It has been reported that the protective effect of THSG against hepatic fibrosis was exerted by strikingly decreasing CCl4-induced phosphorylation of Smad2 and ERK1/2 in the liver tissues of rats." (PMID 36267283, 2022). "In summary, we demonstrated that Daxx plays a pivotal role in TGF-β-induced hepatocyte EMT by inhibiting Smad2 acetylation and phosphorylation during liver fibrosis." (PMID 34359912, 2021). "There were recently reported studies elucidating that human umbilical cord mesenchymal stem cell-derived exosomes (hucMSC-Exo) significantly reduced the expression of collagen and p-Smad2 to alleviate liver fibrosis in vivo." (PMID 33789737, 2021).
liver fibrosis (continued). "Smad signal transduction pathways mediated TGF-β1-induced collagen synthesis through the phosphorylating Smad2/3, which can translocate to the nucleus to regulate the target genes, and thus play a crucial role in the development of liver fibrosis." (PMID 34675811, 2021). "Sirtuin6 deacetylates lysine 54 on Smad2, reducing TGF-β/Smad2 signaling in HSCs and thereby alleviating liver fibrosis." (PMID 34805276, 2021). "In conclusion, our findings demonstrated that miR‐130b‐5p promotes liver fibrosis by regulating SIRT4 via the AMPK/TGF‐β/Smad2/3 signalling pathway." (PMID 34272822, 2021). "The injection of TUDCA has been shown to decrease ER stress and the expressions of TGF-β1 and Smad2/3, resulting in reduced cardiac damage, kidney fibrosis, and liver fibrosis." (PMID 34639105, 2021). "Our study indicated that knockdown of miR‐130b‐5p can alleviate hepatic fibrosis by targeting SIRT4 via the AMPK/TGF‐β/Smad2/3 signalling pathway." (PMID 34272822, 2021). "Taken together, these results suggest that Ufbp1, which lies upstream of Smad2/3, regulates liver fibrosis through Smad3 activation predominately." (PMID 34307359, 2021). "Sirtuin6 is shown to deacetylate Lys54 on Smad2 to prevent liver fibrosis, which suggests that like acetylation, the deacetylation of SMAD2/3 varies, depending on the cell types or related disease models." (PMID 34576109, 2021). "Subsequently, phosphorylated Smad2/3 and Smad4 form a complex and then translocate into the nucleus to regulate the transcription of downstream pro-fibrosis genes, leading to liver fibrosis." (PMID 34675811, 2021). "SMAD family member 2 (SMAD2) is thought to play a critical role in neuronal function and to have a protective role in hepatic fibrosis." (PMID 33643374, 2021). "Loss of TGF-β-activated kinase 1 in hepatocytes leads to liver fibrosis and hepatocellular carcinoma spontaneously by regulating THE Smad2/3 signaling pathway." (PMID 34307359, 2021). "In the canonical pathway, Smad2/3 is activated by phosphorylation but potentially also by lysine acetylation to promote liver fibrosis." (PMID 34805276, 2021). "Previous studies point out that Robo2 regulates both PI3K/Akt and Smad2/3 pathways in liver fibrosis." (PMID 34750987, 2021). "TGF-β—Smad2/3 signaling is a classic fibrotic signaling that promotes tissue fibrosis in multiple diseases such as liver fibrosis, lung fibrosis, and retinal fibrosis." (PMID 33442383, 2020). "The inhibition of phosphorylation of Smad2/3 and Smad4 prevents the downstream signaling pathway, which is responsible for liver fibrosis." (PMID 32365537, 2020). "In liver fibrosis, TGFβ1 upregulates p-Smad2/3, Jagged1, Notch1 and Hes1, leading to trans-differentiation of hepatic stellate cells into myofibroblast cells." (PMID 32724452, 2020). "Glycyrrhizin inhibited pro-fibrotic cytokine TGF-β1-mediated pathways, including Smad2, Smad3 as an active ingredient in astragalus saponins, changed the pathological morphology and prevented the liver fibrosis induced by the bile duct ligation (BDL) model." (PMID 32117622, 2020). "TGF‐β1/Smad2/3 and JAK2/STAT3 pathways are closely associated with the therapeutic effects of PSS, supporting its potential as an effective treatment agent for hepatic fibrosis." (PMID 32233073, 2020). "In line with this, it has been shown in several studies that endoglin can enhance TGF-β1-induced Smad1/5 and/or Smad2/3 phosphorylation in scleroderma fibroblasts, liver fibrosis, and cardiac fibrosis." (PMID 33081058, 2020). "In conclusion, these findings demonstrated that miR-98 targeted HLF and attenuated hepatic fibrosis through the HIF-1α/TGF-β/Smad2/3 signaling pathway." (PMID 32637414, 2020). "The genome-wide profiling in animal models of liver fibrosis found a liver fibrosis-associated lncRNA1 (lnc-LFAR1) that was upregulated in HSCs and its direct binding to Smad2/3 proteins promoted TGFβ and Notch pathway activation and hepatocyte apoptosis." (PMID 30941061, 2019).